CCDC25 (coiled-coil domain containing 25)
Description:
Transmembrane receptor that senses neutrophil extracellular traps (NETs) and triggers the ILK-PARVB pathway to enhance cell motility. NETs are mainly composed of DNA fibers and are released by neutrophils to bind pathogens during inflammation. Formation of NETs is also associated with cancer metastasis, NET-DNA acting as a chemotactic factor to attract cancer cells. Specifically binds NETs on its extracellular region, in particular the 8-OHdG-enriched DNA present in NETs, and recruits ILK, initiating the ILK-PARVB cascade to induce cytoskeleton rearrangement and directional migration of cells. In the context of cancer, promotes cancer metastasis by sensing NETs and promoting migration of tumor cells.
Synonyms: FLJ10853
Tractability: Antibody: UniProt places it where antibodies can reach, with high confidence; its Gene Ontology location is reachable by antibodies, with high confidence; UniProt predicts a signal peptide or a membrane-spanning region. PROTAC: ubiquitination databases record sites on it; its protein half-life has been measured.
Gene: Protein-coding gene on chromosome 8 (27,733,316 to 27,772,653, reverse strand). Ensembl gene ENSG00000147419.
Subcellular location: Cell membrane; Endomembrane system
Subcellular location (Human Protein Atlas): Golgi apparatus; Nucleoplasm; Cytosol
Gene Ontology:
Molecular function: DNA binding; protein binding
Biological process: positive regulation of cell motility
Cellular component: endomembrane system; plasma membrane
Genetic constraint (gnomAD): Loss-of-function variants: 9 observed, 17.01 expected, observed/expected ratio (o/e) 0.53, 90% interval 0.32 to 0.92. The upper end of that interval is the gene's LOEUF score, 0.92, which puts it in group 3 of 6, group 1 being the genes least tolerant of losing a copy. Missense variants: 108 observed, 155.02 expected, observed/expected ratio (o/e) 0.7, 90% interval 0.6 to 0.82. Synonymous variants: 49 observed, 48.69 expected, observed/expected ratio (o/e) 1.01, 90% interval 0.8 to 1.28.
Homologues: Orthologues: chimpanzee CCDC25 (100% identical), macaque CCDC25 (99% identical), dog CCDC25 (98% identical), pig CCDC25 (97% identical), guinea pig CCDC25 (95% identical), mouse Ccdc25 (95% identical), rat Ccdc25 (95% identical), rabbit CCDC25 (85% identical), tropical clawed frog ccdc25 (83% identical), zebrafish ccdc25 (78% identical), Drosophila melanogaster CG4593 (54% identical), Caenorhabditis elegans Y54G11A.2 (53% identical), and 1 more.
Diseases named in the same sentence as CCDC25 in open-access papers:
CCDC25 is named in the same sentence as 32 diseases in open-access papers, as found by Europe PMC text mining. Sharing a sentence is not in itself a finding about the gene and the disease. The quoted sentences say what the papers report.
breast carcinoma (22 papers, 2021 to 2026). "Clinically, high expression of CCDC25 on primary breast cancer cells was associated with reduced metastasis-free survival." (PMID 36253427, 2022). "Therefore, cholesterol-induced tumor metastasis was associated with enhanced CCDC25 expression on cancer cells and NETs formation in metastatic niches in mouse breast cancer model." (PMID 36253427, 2022). "In accordance, higher NET-DNA and CCDC25 levels correlate with worse prognosis in patients with HR+ breast cancer." (PMID 41480760, 2026). "Here we demonstrate that the NET-DNA/CCDC25 axis promotes chemoresistance of luminal breast cancer via inducing EMT in vitro and in vivo, linking TME–cancer cell interactions to chemoresistance." (PMID 41480760, 2026). "Together, our study underscores the translational value of CCDC25-targeted therapy for alleviating chemoresistance for most luminal breast cancer." (PMID 41480760, 2026). "More importantly, we identify NET-DNA/CCDC25 interaction as a key driver of therapeutic resistance, suggesting an observable and targetable pathway to improve therapy sensitivity in breast cancer." (PMID 41480760, 2026). "In line with the clinical data, NET treatment in vitro impaired the cytotoxic efficacy of anthracycline drugs, which was efficiently reduced by CCDC25 knockout in HR+ breast cancer cells, including MCF-7 cells and T47D cells." (PMID 41480760, 2026). "Clinical data reveal that high CCDC25 expression in breast cancer patients correlates with shorter survival, identifying CCDC25 as a potential therapeutic target." (PMID 40568594, 2025). "The promotion of anticancer antibodies against CCDC25 significantly reduced NET-mediated liver metastasis in breast cancer." (PMID 40365275, 2025). "In the prior research, it was found that CCDC25 is a NET-DNA sensor on the surface of breast cancer cells, and that colon cancer cell proliferation can be driven by the interaction between NETs triggered by SKAP1 and CCDC25." (PMID 40148973, 2025). "CCDC25 is overexpressed in breast cancer and can sense NET-DNA to promote breast cancer liver metastasis." (PMID 38817858, 2024). "DNA present in NETs can interact with coiled-coil domain containing 25 (CCDC25) to promote breast cancer metastasis." (PMID 37958984, 2023). "In breast cancer patients, CCDC25 has been detected in cancer cells with a clear membrane staining at the border of the tumor, and higher levels of CCDC25 in the primary tumors have correlated with a reduced survival." (PMID 35309358, 2022). "In conclusion, our study explores a novel mechanism for de novo cholesterol biosynthesis in the regulation of CCDC25 expression, NETs formation and breast cancer metastasis." (PMID 36253427, 2022). "CCDC25-knockout in human breast cancer cells MDA-MB-231 abrogated NET-mediated lung metastases upon intravenous injection of cancer cells in LPS-stimulated mice or the formation of liver metastases upon intrasplenic injection." (PMID 36253427, 2022). "Interrogation of breast cancer cells for a putative NET-DNA receptor capable of mediating signaling resulted in the identification of a coiled coil domain containing protein 25 (CCDC25)." (PMID 35804980, 2022). "The deletion or knockout of CCDC25 in breast cancer cells and colon cancer cells led to the inhibition of NET-mediated lung and liver metastases." (PMID 34067437, 2021). "In the liver metastasis of breast cancer, the transmembrane CCDC25 acted as a NET-DNA receptor on cancer cells to interact with NET and enhance cell motility." (PMID 34830862, 2021). "NETs promote therapeutic resistance of breast cancer via CCDC25." (PMID 41480760, 2026). "Our study offers preclinical evidence supporting that combining CCDC25 inhibition with chemotherapy or radiotherapy may improve breast cancer outcomes." (PMID 41480760, 2026). "High CCDC25 and HMGCR expression was associated with poor prognosis in breast cancer patients." (PMID 40391215, 2025).
breast carcinoma (continued). "One of the key components of NETs, ​​the DNA-histone complex, can recognize and bind to the transmembrane protein CCDC25 on breast cancer cells, thereby activating the ILK-β-parvin pathway to enhance tumor cell motility and lead tumor cells to form distant metastases." (PMID 40391215, 2025). "Furthermore, knockout of the CCDC25 gene in cells has been shown to eliminate NET-mediated breast cancer metastasis." (PMID 38817858, 2024). "Here we used lentivirus-mediated ASPP2 depletion to generate cancer cells with enhanced cholesterol biosynthesis in mouse breast cancer cell 4T1, and investigate the role of cholesterol in regulating CCDC25 expression, NETs formation and tumor metastasis in breast cancer." (PMID 36253427, 2022). "To assess the clinical impact of cholesterol biosynthesis on breast cancer metastasis and NETs, we examined HMGCR, CCDC25 and H3cit expression by IHC staining in a tissue array, including 11 normal and paracancerous breast tissues, 27 primary breast cancer tissues and 17 metastatic tissues." (PMID 36253427, 2022). "In addition, CCDC25 was identified as a transmembrane protein in cancer cells for sensing distant NET-DNA signals, and activation of the ILK-β-parvin pathway downstream of CCDC25 enhanced breast-cancer-cell motility towards NET." (PMID 34831048, 2021). "The overexpression of CCDC25 enhanced the metastasis of breast cancer cells." (PMID 34067437, 2021). "Importantly, targeting CCDC25 effectively suppresses metastasis of breast cancer in a mouse model." (PMID 39015554, 2024). "Furthermore, the expression of CCDC25 in breast cancer tissues is positively correlated with levels of HMGCR and citrullinated histone H3 (H3cit), and high expression of CCDC25 and HMGCR is associated with adverse prognosis in breast cancer patients." (PMID 38817858, 2024). "Clinically, in our cohort of patients with breast cancer receiving NAC, high tumoral expression of CCDC25 was correlated with reduced long-term survival, and this was corroborated by 2 online databases." (PMID 41480760, 2026). "CCDC25 expression was positively correlated with 3-hydroxy-3-methylglutaryl-CoAreductase (HMGCR) and citH3 expression in tissues from breast cancer patients." (PMID 40391215, 2025). "It has been proposed that the cancer cell transmembrane protein CCDC25 acts as an extracellular DNA receptor, which detects NET‐DNA structure and attracts breast cancer cells to form liver metastasis." (PMID 39015554, 2024). "Clinically, enhanced CCDC25 and HMGCR expressions are related with worse prognosis in breast cancer patients." (PMID 36253427, 2022). "HMGCR, CCDC25 and H3cit expressions were negative [score value: ≤ 2 (range 0–2)] in normal and paracancerous tissues, and positive in primary breast cancer tissues and metastatic tissues [score value: > 2 (range 2–12)]." (PMID 36253427, 2022). "High expression of CCDC25 and HMGCR was related with worse prognosis in breast cancer patients." (PMID 36253427, 2022). "Clinically, the expression of CCDC25 was positively correlated with the expression of 3-hydroxy-3-methylglutaryl-CoAreductase (HMRCG), and citrullinated histone H3 (H3cit), in tissues from breast cancer patients." (PMID 36253427, 2022). "Knockout of CCDC25 abrogated breast/CRC metastasis to the liver, and serum NETs could even predict the occurrence of liver mets in early-stage breast cancer patients." (PMID 35954395, 2022). "In addition, we observed that high CCDC25 level was significantly associated with shorter DFS and OS in the patients with HR+ subtypes but not in the patients with HR– breast cancer." (PMID 41480760, 2026).
breast carcinoma (continued). "NET-DNA-mediated stimulation of breast cancer cells resulted in activation of a NET-CCDC25-ILK signaling axis resulting in the activation of the migration/invasion promoting Rho family GTPases, Rac, and cdc42, while depletion of CCDC25, ILK, or β-parvin reduced Rac1/cdc42 activation." (PMID 35804980, 2022). "Besides, pretreatment with neutralizing antibody against CCDC25, but not isotype control, significantly attenuated the NET-induced chemoresistance in HR+ breast cancer cells." (PMID 41480760, 2026).
colon cancer (7 papers, 2021 to 2025). "Moreover, a high expression of CCDC25 in primary breast and colon cancer cells was associated with a poor prognosis of the patients." (PMID 34067437, 2021). "Coiled-coil domain containing 25 (CCDC25) has been identified as a target molecule that mediates liver metastasis in colon cancer." (PMID 36211267, 2022).
gastric cancer (3 papers, 2023 to 2024). A primary or metastatic malignant neoplasm involving the stomach. "We further analyzed the differences in chemosensitivity and targeted drug sensitivity in gastric cancer patients with high and low CCDC25 expression." (PMID 37480055, 2023). "Subsequent investigations revealed that NETs could induce CCDC25 expression in gastric cancer cells, leading to increased proliferation of these cells." (PMID 38664728, 2024). "In addition, the effect of CCDC25 expression on chemotherapeutic drugs in gastric cancer is based on the Shengxin database, which needs to be verified and analyzed via more complete basic trials and clinical data." (PMID 37480055, 2023). "Moreover, drug sensitivity analysis showed that gastric cancer patients with low CCDC25 expression had a better response to drugs, which is relevant information for guiding clinicians in selecting drug treatments." (PMID 37480055, 2023). "We further analyzed the biological function of CCDC25 in gastric cancer using bioinformatics." (PMID 37480055, 2023). "Our sequencing results show that CCDC25 may also affect PI3K and MAPK pathways, research has shown that the CCDC family gene CCDC134 can suppress the progression of gastric cancer by inhibiting the MAPK pathway." (PMID 38570766, 2024).
cholangiocarcinoma (2 papers, 2021 to 2022). A carcinoma that arises from the intrahepatic biliary tree (intrahepatic cholangiocarcinoma) or from the junction, or adjacent to the junction, of the right and left hepatic ducts (hilar cholangiocarcinoma). "It has been found that CCDC25 overexpression in cholangiocarcinoma (CCA) can enhance the migration ability of CCA cells." (PMID 36211267, 2022).
colorectal cancer (2 papers, 2021 to 2026). A primary or metastatic malignant neoplasm that affects the colon or rectum. "Since the expression of either KLK11 or CCDC25 was associated with the metastasis of colorectal cancers, the expressions of CCDC25 and KLK11 in CCA with or without lymph node metastasis were analyzed." (PMID 34067437, 2021).
bladder cancer (1 paper, 2025). "By identifying three uEV biomarkers (mucin-1 (MUC-1), coiled-coil domain containing 25 (CCDC25), and solute carrier family 2 member 1 (GLUT1)), Pt@CP-based immunoassays are able to detect bladder cancer with high clinical specificity and sensitivity." (PMID 40072370, 2025).
giant cell arteritis (1 paper, 2024). "In this study, we identified an intronic variant of CCDC25 that constitutes a risk factor for giant cell arteritis." (PMID 38734017, 2024). "Additionally, three new genomic associations with giant cell arteritis were identified at the 8p21.1 (CCDC25, rs11782624; p=1·28 × 10–8; OR 1·18 [95% CI 1·12–1·25]), 15q26.1 (MFGE8, rs8029053; p=4·96 × 10–8; OR 1·19 [1·12–1·26]) and 17q11.2 (VTN, rs704; p=2·75 × 10–9; OR 0·84 [0·79–0·89]) regions." (PMID 38734017, 2024).
head and neck squamous cell carcinoma (1 paper, 2022). A squamous cell carcinoma that arises from any of the following anatomic sites: lip and oral cavity, nasal cavity, paranasal sinuses, pharynx, larynx, and salivary glands. "As for head and neck squamous cell carcinoma (HNSC), CCDC25 expression in samples with HPV+ was significantly higher than that in samples with HPV−." (PMID 36211267, 2022).
lung carcinoma (1 paper, 2023). "Although few samples had mutations in PBK, we observed that mutations in CNV accounted for the majority of PBK gene DNA alterations in all lung cancer patients and found a high proportion of LUAD patients with CNV with multiple tumor suppressor genes, such as CCDC25, SCARA5 and EPHX2." (PMID 37993518, 2023).
lymph node metastasis (1 paper, 2021). "The correlation between the CCDC25 and KLK11 expressions in the cancerous tissues of CCA with/without lymph node metastasis was analyzed using Spearman’s test." (PMID 34067437, 2021). "However, a significant correlation was observed between KLK11 and CCDC25 expressions in CCA with lymph node metastasis (p = 0.028 and r = 0.593), but not in CCA without lymph node metastasis (p = 0.417 and r = 0.600)." (PMID 34067437, 2021).
metastatic cancer (1 paper, 2022). A carcinoma which has spread from the original site of growth to another anatomic site. "However, the expression of HMGCR was positively correlated with the expression of CCDC25 and H3cit in 44 primary and metastatic cancer tissues (P < 0.05), and the expression of CCDC25 and H3cit was also positively correlated (P < 0.05)." (PMID 36253427, 2022).
renal carcinoma (1 paper, 2024). A carcinoma arising from the epithelium of the renal parenchyma or the renal pelvis. "The overexpression of CCDC25 reduced the proliferation and migration of renal cancer cells while promoting apoptosis." (PMID 38570766, 2024). "Apoptosis experiments showed that overexpression of CCDC25 promoted apoptosis of renal carcinoma cell lines." (PMID 38570766, 2024). "First, we examined the expression of CCDC25 in several renal cancer cell lines and a normal renal cell line (HK2) using Western blot analysis." (PMID 38570766, 2024). "We conducted RNA transcriptome sequencing analysis on 786–0 cells overexpressing CCDC25 and normal 786–0 cells to explore the potential mechanism of CCDC25 in renal cancer." (PMID 38570766, 2024). "Overexpression of CCDC25 in renal cancer cell lines resulted in reduced proliferation and migration." (PMID 38570766, 2024). "The results showed that the expression of CCDC25 in the normal renal cell line HK2 was significantly higher than in the other renal cancer cell lines." (PMID 38570766, 2024). "We first overexpressed YAP through plasmid transfection, to verify whether CCDC25 affects renal cancer cells through YAP protein." (PMID 38570766, 2024).
renal clear cell carcinoma (1 paper, 2024). "Our study reveals a novel role for CCDC25 in the pathogenesis and progression of clear cell renal cell carcinoma (ccRCC)." (PMID 38570766, 2024). "We assessed the proliferation of ccRCC (clear cell renal cell carcinoma) cell lines under conditions of CCDC25 overexpression using the CCK8 assay." (PMID 38570766, 2024). "In ccRCC (clear cell renal cell carcinoma), the expression of CCDC25 within tumors is markedly lower than in normal tissues." (PMID 38570766, 2024). "Thus, CCDC25 also functions to suppress the growth of renal clear cell carcinoma in vivo." (PMID 38570766, 2024).
skin cutaneous melanoma (1 paper, 2022). "In addition, the skin cutaneous melanoma (SKCM) with metastasis had a higher CCDC25 expression compared with the SKCM group." (PMID 36211267, 2022).
steatosis (1 paper, 2025). Increased lipid within the cytoplasm of cells. "Specifically, H4C1, OIT3, ANPEP, CCDC25 and KLHL41 were identified as potential biomarkers for steatosis, GP1BA as a candidate marker for MASH and C7, IGHD and GNB1 as potential biomarkers for fibrosis severity." (PMID 41301514, 2025).